DOCK8-AS1 (DOCK8 antisense RNA 1)
Synonyms: C9orf66; FLJ31158
Gene: Long non-coding RNA gene on chromosome 9 (212,824 to 215,893, reverse strand). Ensembl gene ENSG00000183784.
Diseases named in the same sentence as DOCK8-AS1 in open-access papers:
DOCK8-AS1 is named in the same sentence as 3 diseases in open-access papers, as found by Europe PMC text mining. Sharing a sentence is not in itself a finding about the gene and the disease.
DOCK8-AS1 shares sentences with these, for which no sentence is quoted: tumor (2 papers); melanoma (1); nevus (1).